LYZ (lysozyme)
Diseases named in the same sentence as LYZ in open-access papers (continued):
Sharing a sentence is not in itself a finding about the gene and the disease.
tumor (continued). "Gene and pathway enrichment analysis revealed that the ‘Tumor_2’ population upregulates fucosylation, hydroxylation and HIF pathways, and genes associated with the basal-like tumor subtype (BTNL8, AGR3 and LYZ)." (PMID 35995947, 2022). "The samples treated with lysozyme performed slightly better than cellulase-treatment on MDA MB-435 tumor cells." (PMID 36142196, 2022). "LYZ expression, 84% of which was attributed to macrophages and monocytes, was highest in a corner of the tumor where those cell populations had relatively low abundance." (PMID 35046414, 2022). "The later stage of tumor development affects the immune ability of patients and then affects the secretion level of lysozyme protein in the mouth." (PMID 34925025, 2021). "Many experimental studies on tumor cells have confirmed that lysozyme can inhibit the proliferation of tumor cells." (PMID 34925025, 2021). "The anti-tumor mechanism of lysozyme can be summarized as direct activation of immune effectors and indirect enhancement of host immunity." (PMID 34925025, 2021). "Human CD2high pDCs infiltrated in TME express high levels of granzyme B, TRAIL and lysozyme, which limit proliferation of tumor cells and mediate contact-dependent killing of tumor cells." (PMID 34359674, 2021). "Scientists have verified the inhibitory effect of lysozyme on tumors through tumor cell mixing, peritumoral and intratumoral treatment, systemic injection, oral treatment, indirect administration, or combination with other drugs." (PMID 34925025, 2021). "Through participating in immunization activities by presenting antigens, LYZ regulates the tumour microenvironment and influences cancer processes." (PMID 33047898, 2020). "About 50% of IDO1+ tumor cells were Lysozyme-positive, demonstrating a significant contribution of Paneth cells to Ido1 expression in the neoplastic epithelium." (PMID 32444775, 2020). "As an antimicrobial peptide, lysozyme has many functions, including antimicrobial properties and anti-tumor and anti-inflammatory functions." (PMID 32438389, 2020). "The cytoplasm of tumor cells and secretion demonstrated marked reactivity with lysozyme antibody on immunohistochemical stain." (PMID 30621725, 2019). "Both the cytoplasm of tumor cells and luminal secretion were diffusely and strongly positive for lysozyme immunohistochemical stain and Periodic acid–Schiff with diastase digestion." (PMID 30621725, 2019). "The histological classification of CTVT was mainly based on positive immunostaining for lysozyme (encoded by LYZ), α1-antitrypsin (encoded by SERPINA1), and vimentin (encoded by VIM) in about 30%–50% of the tumor cells." (PMID 29634949, 2018). "Similar to Apc-mutant tumours, we observed ectopic production of Paneth cells (Lysozyme+) throughout the lesions." (PMID 28695896, 2017). "We observed both increased lysozyme‐positive cell abundance and zone of OLFM4 expression in Huwe1‐deficient tumours." (PMID 28003334, 2017). "In our study, Paneth cells were detected by immunostaining for lysozyme, whereas tumor area was determined by nuclear localization of β-catenin." (PMID 28176811, 2017). "After 48 h, the lysozyme/DNase I mixture was injected into tumors and then FDGlcU was again i.v. injected and tumor fluorescence was imaged." (PMID 25688562, 2015). "Immunohistochemically, most of the tumor cells stained strongly for amylase, lysozyme, α-1-antichymotrypsin (α1ACT), epithelial membrane antigen (EMA), and S-100 protein and also showed positive for cytokeratin 7 and E-cadherin." (PMID 24191209, 2013). "The locus 12q15 (lead SNP rs11177644) was associated with a pattern driven by two cis eQTLs, LYZ and YEATS4, and including 34 trans eQTLs, several of them tumor-related genes." (PMID 22144904, 2011). "In vitro studies demonstrated that the macrophages resident in a tumour mass are responsible for relasing lysozyme in large amounts." (PMID 938609, 1976).
tumor (continued). "By reprogramming myeloid cells and enhancing immune infiltration into the tumor microenvironment, the use of LYZ with current immunotherapeutic approaches, such as immune checkpoint inhibition, may also improve anticancer efficacy." (PMID 41514850, 2025). "Supporting these findings, a recent study using an orthotopic murine pancreatic ductal adenocarcinoma (PDAC) tumor model demonstrates that the GLUT1 depletion in TAMs via lysozyme M‐cre (LysMcre) improved natural killer and CD8+ T cell activity and inhibited tumor progression." (PMID 40223597, 2025). "These Paneth-like cells, identified by markers such as DEFA6 and LYZ, are essential for propagating tumor organoids and are found in tumor regions where cell adhesion is lost, suggesting they play a key role in maintaining the CSC niche and supporting tumor growth." (PMID 41002393, 2025). "Consequently, our results pave the way for exploiting the physiological increase in P and LYZ in cancer cells as a potential Achilles’ heel of tumor cells." (PMID 40046560, 2025). "The regulators in C1 LYZ+ tumor cells were mainly FOXA2, PDX1, GATA6, and PPARG." (PMID 40230840, 2025). "Initially, researchers thought that the tumour cells originated from the olfactory mucosa Bowman’s glands in the ethmoid region, but a later immunohistochemical study using lysozyme staining found that the tumour cells’ staining pattern was the same as that of the serous glands." (PMID 40144068, 2025). "Significant associations between LYZ expression and particular immune cell types were found using immune infiltration analysis, suggesting that LYZ may have an impact on the tumor microenvironment." (PMID 41514850, 2025). "Moreover, many of these genes are associated with stemness, such as MUC5B, as well as tumor biology, including REG4, LYZ, EREG, KRT23, and RAMP1, which were also identified in a previous CRC single-cell study." (PMID 39350339, 2024). "Immunohistochemistry reveals CD68, CD163, lysozyme, and CyclinD1 expression in the tumor cells." (PMID 38706599, 2024). "Multiple types of cells were found within the tumor organoid in a heterogeneous manner, such as paneth cells expressing Lysozyme (Lysz) and epithelial cells expressing Villin 1 (Vill), while a lower abundance of Mucin2 (Muc2)-expressing goblet cells were observed in the tumor organoids." (PMID 38954022, 2024). "Moreover, it exhibits rapid real-time response to acidic environments and displays enhanced fluorescence intensity, enabling the real-time tracking of probe entry into tumor cells as well as intracellular lysozyme accumulation." (PMID 38933449, 2024). "When the primary objective of the study was the overall survival of tumor-bearing animals, the use of plasma samples collected from lysozyme-treated mice in conjunction with the surgical removal of the primary tumor increased the number of cured animals from 10% to 40%." (PMID 37446691, 2023). "Similarly, lysozyme has demonstrated tumor-preventive effects in vivo, an outcome mediated by immune cell stimulation and enhanced tumor immunogenicity." (PMID 37761179, 2023). "This expression was considered inconclusive but suggested that tumor cells might acquire macrophagic properties and execute lysozyme digestion, which is compatible to previous CIC reports." (PMID 35847959, 2022). "However, we have demonstrated that restricting the analysis to initial tumor stages (i.e., stage II) is sufficient to confirm the prognosis value of LYZ levels in CRC." (PMID 34831152, 2021). "To determine whether the lysozyme expression and stem cell phenotypes were maintained in tumour tissue, we analysed lysozyme and OLFM4 expression in these tumours." (PMID 28003334, 2017). "Indeed, we have used the MD4 BCR transgenic mouse model (in which all B cells express a BCR specific for hen egg lysozyme) to evaluate the putative role of BCR activation by autoantigens in the tumour development process." (PMID 27297662, 2016).
tumor (continued). "Likewise, lysing E. coli (lux/βG) in the tumor by intratumoral injection of lysozyme and DNase I to release beta-glucuronidase also significantly increased hydrolysis of the glucuronide probe." (PMID 25688562, 2015). "We conclude that under well defined conditions serum lysozyme activity may be a useful marker of macrophage mediated host responses to a tumour." (PMID 766806, 1976). "Therefore, it was suggested that the secreted LYZ binds to the outer surface of the tumor cells." (PMID 40046560, 2025). "Interestingly, Paneth cells are producers of antimicrobial peptides that interact with the gut microbiota and modulate immune cells, showing a contrasting pattern, being increased in tumor tissue, as indicated by the upregulation of the genes LYZ, DEFA1, SOX9, and WISP1." (PMID 41303610, 2025). "Additionally, these neutrophils may exhibit increased cytotoxicity, releasing reactive oxygen species (ROS) and enzymes like elastase and lysozyme to directly kill tumor cells." (PMID 39960903, 2025). "Immune cell recruitment and activation within the GBM microenvironment may be influenced by LYZ, potentially impacting tumor-immune interactions and disease progression, as indicated by the variations in immune cell abundance between high and low LYZ expression groups." (PMID 41514850, 2025). "Furthermore, neutrophils can undergo degranulation, a process during which molecules such as defensins, myeloperoxidase, and lysozyme are secreted from intracellular granules into the extracellular environment, leading to tissue damage and promoting tumor metastasis." (PMID 39654896, 2024). "Moreover, the treatment with lysozyme leads to a regression in the growth of some tumor cells." (PMID 30597935, 2018). "The tumor comprised numerous multinucleated giant cells of the osteoclastic type (positive for tartrate-resistant acid phosphatase- TRAP- and lysozyme), evenly distributed among mononuclear cells (both rounded and spindle-shaped)." (PMID 41908959, 2026). "In summary, lysozyme inhibition is the initial step in this process, while CX3 CR1 and PD-L1 mediate the key steps in the transformation of phagocytes to a pro-tumor phenotype." (PMID 40381082, 2025). "The tumor group exhibited statistically significant differences in SPP1, LYZ, and MCM5 expression levels in NK/T cells, myeloid cells, epithelial cells, and other cells compared to the healthy control group." (PMID 41384115, 2025). "Based on the expression of key marker genes-MUC1 (tumor region), LYZ (immune region), COL14A1 (stromal region), and SFTPC (normal region)—we classified the niches into tumor, immune-stromal, and normal regions across all spatial transcriptomic samples." (PMID 40396179, 2025). "In the present study, four distinct tumor cell subsets, namely RPS4Y1+ tumor cells, LYZ+ tumor cells, CPE+ tumor cells, and MKI67+ tumor cells, were identified for the first time." (PMID 40230840, 2025). "Recent studies have highlighted a correlation between high levels of lysozyme (LYZ) expression and cancer progression in different types of tumors, so LYZ has been indicated as a potential tumor biomarker." (PMID 40046560, 2025). "Using a self-assembly system of lysozyme and cysteine, we co-loaded glucose oxidase (GOx) and catalase (CAT) in a one-step process, aiming to simultaneously achieve dual functions of anti-tumor recurrence and anti-postoperative adhesion." (PMID 40358287, 2025). "Divergent LYZ and LMAN2L endothelial trends, coupled with cohort-specific CTSF dynamics in T cell subsets, underscore spatial or molecular heterogeneity in tumor microenvironments." (PMID 40381082, 2025). "In contrast, Paneth cell markers, including defensin alpha 1 (DEFA1), lysozyme (LYZ), and SOX9, were upregulated in tumor tissue." (PMID 41303610, 2025).
tumor (continued). "C0 RPS4Y1+ tumor cells mainly corresponded to the M3 and M2 modules, C1 LYZ+ tumor cells mainly corresponded to the M4 module, C2 CPE+ tumor cells mainly corresponded to the M1 module, and the specificity of C3 MKl67+ tumor cells was not very significant." (PMID 40230840, 2025). "Through a one-step method involving cysteine-reduced lysozyme-induced amyloid-like self-assembly, the film was co-loaded with GOx and CAT to achieve synergistic anti-adhesion and anti-tumor recurrence effects." (PMID 40358287, 2025). "Immunohistochemical staining of the second resection specimen showed that tumor cells were positive for CD68, CD163, CD4, INI-1 and ATRX, Scattered focal positivity for lysozyme, and some positive for S-100 and LCA." (PMID 40231251, 2025). "Box plots showed that the expression of LYZ, LCN2, and CEACAM5 from external datasets was significantly higher in tumor samples compared to normal samples (p < 0.01), complementing our findings." (PMID 39456726, 2024). "Ingenuity pathway analysis (IPA) of the human scRNA-seq data from primary tumor and metastasis samples suggested hepatocyte nuclear factor 4 alpha (HNF4A) as an upstream regulator of LYZ+ cancer cells compared to LYZ− cancer cells." (PMID 38659853, 2024). "IPA of the human scRNA-seq data from primary tumor and metastasis samples suggested HNF4A as an upstream regulator of LYZ+ cancer cells compared to LYZ- cancer cells." (PMID 39535280, 2024). "In GBM, differential expression of LYZ and PIK3AP1 alters the immune and tumor microenvironment leading to worse prognoses." (PMID 37189838, 2023). "On the other hand, the expression of marker genes for other cell types, such as LYZ (Paneth cell marker) and SOX9 (intestine progenitor cells), were enriched in tumor epithelial cells and LYZ expression was further verified by IHC staining." (PMID 35974387, 2022). "These analyses revealed protein expression of Paneth cell markers Lysozyme and MMP7 in IDO1+ tumor cells." (PMID 32444775, 2020). "Only two proteins—DEFA1 (elevated in tumors) and LYZ (significantly decreased in tumors)—could robustly differentiate disease recurrence, whereas the authors found lipid profiles were more discriminatory for disease recurrence in addition to discriminating tumor versus NAT." (PMID 32742246, 2020). "Immunohistochemically, the tumor cells showed typically positive for Vimentin(27/27), CD68(13/13), and MAC387(2/2), and AAT(13/14), Lysozyme(11/12), ACT(10/12) showed positive in most cases." (PMID 22221822, 2012). "The tumor cells in the present case apparently revealed positive expression of specific histiocytic markers, such as CD68 (KP-1), and lysozyme." (PMID 23075171, 2012). "The tumour usually spares the mucosa, infiltrates muscularis propria and peri-appendiceal fat and can stain positively for mucin, CEA, cytokeratin, lysozyme, chromogranin A, serotonin and synaptophysin." (PMID 19171048, 2009). "Immunohistochemical staining in the tumor cells was positive for CD163, CD68, lysozyme, CD45, and NSE." (PMID 17324277, 2007). "Therefore, the tumor progression in HCC cells can be related and promoted by the ectopic expression of LYZ." (PMID 40046560, 2025). "In addition, we found that the expression of some NRGs had positive correlations with tumor-infiltrating immune cells, including PARVB, SPP1, and LYZ." (PMID 37716978, 2023). "However, there has been limited coverage of ALB, LYZ and S100A14 in the field of PC, especially in the tumor immune microenvironment." (PMID 35953822, 2022).
tumor (continued). "The shMLL1 human Ls174T xenografts and sphere cells showed enhanced differentiation with an increase in the expression of the Paneth cell-specific genes DEFA5 and LYZ and the goblet cell markers MUC2 and ITF, as was also observed in the β-catGOF mouse tumor model." (PMID 33349639, 2020). "The tumor cells expressed CD68 and CD163, and lysozyme and fascin, when tested." (PMID 30084011, 2018). "Therefore, the LYZ, LCN2, CEACAM5, and AGRN genes, with specific expression along the malignant continuum, may serve as markers for CRC precancerous diagnosis and tumor progression detection." (PMID 39456726, 2024). "It has been reported that YTHDF1 can promote lysozyme in dendritic cells to regulate the degradation of tumor neoantigens, and the key to this process is that YTHDF1 can accurately recognize the m6A modification process of tumor neoantigens and enhance their translation level." (PMID 34993195, 2021). "qRT-PCR analysis of these three FACS sorted populations showed that Notch1-derived lineages (in blue) express intermediate levels of both Lgr5 and differentiation markers, such as lysozyme, between non-labelled cells (in red) and Notch1-expressing tumour cells (in green)." (PMID 30696875, 2019). "The tumor in this case was an infiltrating solid, trabecular, and microglandular pattern and, in most ACC, the tumor cells were immunohistochemically positive for amylase, lysozyme, α1ACT, S-100 protein, and EMA but were negative for estrogen receptor, progesterone receptor, and HER2 protein." (PMID 24191209, 2013). "However, due to the overly high cell density of the tumour nest and the limited IMC resolution, some adjacent tumour cells and infiltrated immune cells were recognised as epithelial–immune dual feature cells, such as Clusters 4 (KRT5+, KRT19+, CD20+ and CD79A+) and 14 (KRT5+, KRT19+ and LYZ+)." (PMID 37349991, 2023). "We assessed the expression of EDB-FN1 in tumor tissues derived from our PDAC models by both RNA-seq and IF using the L19 antibody, while the KSF antibody (specific to hen-egg lysozyme) was used as negative control." (PMID 39773310, 2025). "Although some of the IHC findings raised the possibility of a HS, as the tumour was also positive for CD68 and lysozyme, the morphology was not typical as the cells found in HS are large to round with focal spindling." (PMID 36344905, 2023). "The tumor cells were weakly positive for CD68 and lysozyme, negative for CD163, and positive for CD4, which excluded rare tissue cell-derived tumors." (PMID 36871023, 2023). "Immunohistochemistry study revealed that the tumor cells were positive for CD4 and CD30, and were negative for cytokeratin, CD3, CD20, CD68, CD163, lysozyme, ALK, S-100, and desmin." (PMID 32547956, 2020). "For the diagnosis of BPDCN, the tumor should be negative for other myelomonocytic, NK, T, and B lineage markers (CD34, CD8, MPO, lysozyme, PAX5, CD20, CD79a, EBV, and T-cell receptor protein)." (PMID 31752482, 2020). "The author pointed out that the high expression of lysozyme, which was specific for histiocytic lymphoma, in PVS cells strongly suggested that PVS was not of host origin but derived from the xenografted tumor cells." (PMID 23762119, 2013). "Tumor immunophenotype was characterized by a strong expression of conventional myeloid antigens (CD13, CD33, CD15, MPO), although no monocytic (CD14, CD64, CD11c, CD11b, lysozyme), megakaryoblastic (CD61, CD41) and lymphoid (CD7, CD19, iCD79a, CD56, CD2) markers were found." (PMID 36980947, 2023).